ALOXE3 (arachidonate epidermal lipoxygenase 3)
Description:
Non-heme iron-containing lipoxygenase which is atypical in that it displays a prominent hydroperoxide isomerase activity and a reduced lipoxygenases activity. The hydroperoxide isomerase activity catalyzes the isomerization of hydroperoxides, derived from arachidonic and linoleic acid by ALOX12B, into hepoxilin-type epoxyalcohols and ketones. In presence of oxygen, oxygenates polyunsaturated fatty acids, including arachidonic acid, to produce fatty acid hydroperoxides. In the skin, acts downstream of ALOX12B on the linoleate moiety of esterified omega-hydroxyacyl-sphingosine (EOS) ceramides to produce an epoxy-ketone derivative, a crucial step in the conjugation of omega-hydroxyceramide to membrane proteins. Therefore plays a crucial role in the synthesis of corneocytes lipid envelope and the establishment of the skin barrier to water loss. In parallel, it may have a signaling function in barrier formation through the production of hepoxilins metabolites. Also plays a role in adipocyte differentiation through hepoxilin A3 and hepoxilin B3 production which in turn activate PPARG (By similarity). Through the production of hepoxilins in the spinal cord, it may regulate inflammatory tactile allodynia (By similarity).
Synonyms: eLOX-3; eLOX3; E-LOX; ARCI3; LI5
Tractability: Small molecule: it belongs to a druggable protein family. Antibody: the Human Protein Atlas places it where antibodies can reach. PROTAC: ubiquitination databases record sites on it.
Gene: Protein-coding gene on chromosome 17 (8,095,900 to 8,119,047, reverse strand). Ensembl gene ENSG00000179148.
Subcellular location: Cytoplasm
Subcellular location (Human Protein Atlas): Cytosol; Plasma membrane
Pathways (Reactome):
Metabolism: Synthesis of 12-eicosatetraenoic acid derivatives
Gene Ontology:
Molecular function: hydroperoxy icosatetraenoate dehydratase activity; hydroperoxy icosatetraenoate isomerase activity; intramolecular hydroxytransferase activity; oxidoreductase activity, acting on single donors with incorporation of molecular oxygen, incorporation of two atoms of oxygen; protein binding; iron ion binding; metal ion binding
Biological process: arachidonate metabolic process; hepoxilin biosynthetic process; linoleic acid metabolic process; lipoxygenase pathway; sphingolipid metabolic process; ceramide biosynthetic process; establishment of skin barrier; fat cell differentiation; peroxisome proliferator activated receptor signaling pathway; sensory perception of pain; lipid oxidation
Cellular component: cytosol; cytoplasm
Genetic constraint (gnomAD): Loss-of-function variants: 78 observed, 90.93 expected, observed/expected ratio (o/e) 0.86, 90% interval 0.71 to 1.04. The upper end of that interval is the gene's LOEUF score, 1.04, which puts it in group 4 of 6, group 1 being the genes least tolerant of losing a copy. Missense variants: 923 observed, 931.96 expected, observed/expected ratio (o/e) 0.99, 90% interval 0.94 to 1.05. Synonymous variants: 355 observed, 381.52 expected, observed/expected ratio (o/e) 0.93, 90% interval 0.85 to 1.02.
Homologues: Orthologues: chimpanzee ALOXE3 (99% identical), macaque ALOXE3 (99% identical), rabbit ALOXE3 (91% identical), pig ALOXE3 (90% identical), guinea pig ALOXE3 (89% identical), mouse Aloxe3 (88% identical), rat Aloxe3 (88% identical), dog ALOXE3 (83% identical), zebrafish si:dkey-17e16.9 (41% identical). Paralogues in human: ALOX12B (52% identical), ALOX15B (51% identical), ALOX5 (39% identical), ALOX12 (36% identical), ALOX15 (35% identical).
Diseases named in the same sentence as ALOXE3 in open-access papers:
ALOXE3 is named in the same sentence as 47 diseases in open-access papers, as found by Europe PMC text mining. Sharing a sentence is not in itself a finding about the gene and the disease. The quoted sentences say what the papers report.
autosomal recessive congenital ichthyosis (15 papers, 2012 to 2025). Autosomal recessive form of inherited ichthyosis. "Pathogenic variants in ALOXE3 have been described in human patients with autosomal recessive congenital ichthyosis." (PMID 41057024, 2025). "It has been established that ALOX12, ALOX12B, and ALOXE3 mutations can cause autosomal recessive congenital ichthyosis (ARCI)." (PMID 36684424, 2022). "and mutations in ALOXE3 have been reported to be associated with the development of autosomal recessive congenital ichthyosis (ARCI).But little is known about the function of ALOXE3 in cancer and its mechanism of action." (PMID 35265525, 2022). "Based on clinical examination and genetic testing, a diagnosis of SICB was confirmed, with mutations identified in genes commonly associated with autosomal recessive congenital ichthyosis, such as ALOX12B, TGM1, ALOXE3, CYP4F22, and PNPLA1." (PMID 40193669, 2025). "Autosomal recessive congenital ichthyosis (ARCI) is associated with mutations in at least 10 genes, such as TGM1, ALOXE3, ALOX12B, ABCA12, and others." (PMID 40565081, 2025). "Genetic evidence has linked missense and splice site mutations in ALOXE3 and ALOX12B to the incidence of autosomal recessive congenital ichthyosis (ARCI)—a severe disorder of keratinization." (PMID 38612771, 2024).
ichthyosis (13 papers, 2012 to 2025). Disorders of cornification that are characterized by visible scaling and/or hyperkeratosis of most or all of the skin. "Mutations in the LOX gene family, specifically arachidonic acid 12-lipoxygenase (ALOX12B) and arachidonate lipoxygenase 3 (ALOXE3), are common causes of ichthyosis." (PMID 39430757, 2024). "12R-LOX is important in skin function; mutations in the ALOX12B gene lead to ichthyosis, as do mutations in the ALOXE3 gene." (PMID 36765904, 2023). "A genetic analysis of patients with ichthyosis over a period of 26 years revealed 170 families with mutations in ALOX12B or ALOXE3 in our laboratories; a further 54 families were contributed by other coauthors within the ERN-Skin network." (PMID 33435499, 2021). "To date, multiple genes have been shown to be associated with ichthyosis, including ALOXE3, ALOX12B, TGM1, CYP4F22, NIPAL4, and ABCA12." (PMID 24278723, 2012). "For this reason, mutations in the ALOXE3 gene lead to ichthyosis." (PMID 36765904, 2023). "There are 6 genes currently known to be associated with ichthyosis: ALOXE3, ALOX12B, TGM1, CYP4F22, NIPAL4, and ABCA12, and although thought to be unrelated, both the probands from family 1 and family 2 harboured an identical novel missense variant, c.G4676T, p.Gly1559Val in ABCA12." (PMID 24278723, 2012). "We assume that the identified missense variant in the affected Chihuahua of this study impairs the normal function of the ALOXE3 protein and the formation of a functioning corneocyte lipid envelope, which ultimately leads to a disorder of cornification that manifests as ichthyosis." (PMID 41057024, 2025). "ALOXE3, epidermal LOX type 3, converts fatty acid substrates to specific epoxyalcohol derivatives using R-hydroperoxides, is involved in late epidermal differentiation and ichthyosis." (PMID 34336641, 2021). "Additionally, 15 genes involved in lipid metabolism were differentially expressed, some directly involved in ichthyosis, e.g., ABCA12, ALOX5, ALOX12B, ALOXE3, CYP4F2, and 2 elongation of very long chain fatty acid protein (ELOV) genes." (PMID 32544098, 2020).
glioblastoma (11 papers, 2021 to 2025). The most malignant astrocytic tumor (WHO grade IV). "ALOXE3 deficiency not only enhances the survival and migration of cancer cells but also supports glioblastoma growth in immunodeficient nude mice." (PMID 39633985, 2024). "Another study revealed that ALOXE3 is markedly downregulated in human glioblastoma (GBM) and that ALOXE3 deficiency renders GBM cells resistant to ferroptosis, promoting GBM cell survival." (PMID 34764976, 2021). "Compared to normal human brain tissue, ALOXE3 expression is significantly diminished in glioblastoma tissue." (PMID 39633985, 2024). "We conducted a pan-cancer Kaplan–Meier survival analysis for ALOXE3 and found that it serves as a better prognostic indicator in glioblastoma multiforme (GBM), while it is associated with unfavorable outcomes in colon adenocarcinoma (COAD) and uterine corpus endometrial carcinoma (UCEC)." (PMID 38429254, 2024). "Xinzhi Yang 98 revealed that miR-18a accelerated glioblastoma advancement by directly inhibiting ALOXE3-mediated ferroptotic and antimigration activities." (PMID 35342359, 2022). "This miRNA has been shown to suppress expression of ALOXE3 in glioblastoma cells." (PMID 36876051, 2023). "MiR-18 downregulates ALOXE3 and increases glioblastoma development and migration activity." (PMID 37240889, 2023). "Besides, ALOXE3 knock-down has enhanced secretion of 12-HETE from glioblastoma cells, decreasing migration of these cells through activation of GsPCR/PI3K/Akt axis." (PMID 36876051, 2023). "ALOXE3 was reported to induce ferroptosis similar to ALOX12 in glioblastoma (GBM) cells." (PMID 37386007, 2023). "In glioblastoma cells (GBM), ALOXE3 was identified as a tumor promoter." (PMID 37240889, 2023). "Significant changes in intracellular lipid metabolism were found in glioblastoma (GBM), in which the expression of ALOXE3 was significantly down regulated." (PMID 36408273, 2022). "ALOXE3 as a paralog of ALOX12B, inhibits glioblastoma tumor migration." (PMID 35768785, 2022).
colorectal cancer (6 papers, 2021 to 2024). A primary or metastatic malignant neoplasm that affects the colon or rectum. "On the contrary, IFNG is higher expressed in the left-colorectal cancer high-risk group, while Aloxe3 is more highly expressed in the right-colorectal cancer high-risk group." (PMID 35265525, 2022). "Furthermore, the novel ferroptosis inducer, talaroconvolutin A, has been shown to trigger ferroptosis and suppress colorectal cancer cell growth by modulating ALOXE3 expression and other genes." (PMID 39633985, 2024). "Upregulated arachidonate lipoxygenase 3 (ALOXE3) can promote ferroptosis in colorectal cancer." (PMID 34395526, 2021). "Talaroconvolutin A, a novel inducer of ferroptosis, effectively inhibited the growth of xenogeneic colorectal cancer cells by downregulating SLC7A11 and upregulating ALOXE3 in vivo experiments." (PMID 38082448, 2023).
hepatocellular carcinoma (5 papers, 2018 to 2024). A malignant tumor that arises from hepatocytes. "Transcriptional upregulation of ALOXE3 by YAP promotes lipid peroxide accumulation and induces ferroptosis, making the YAP-ALOXE3 signaling pathway a potential biomarker for predicting ferroptosis-induced responses in hepatocellular carcinoma cells." (PMID 39633985, 2024). "We first analyzed the correlation between YAP mRNA expression and ALOXE3 in hepatocellular carcinoma using data from the TCGA." (PMID 34977009, 2021). "In light of evidence that Aloxe3 is a potentially novel hepatocyte fasting-responsive factor in mice and in isolated murine hepatocytes, we evaluated whether this factor is expressed in isolated human hepatocytes and in Huh7 and HepG2 human hepatoma cell lines." (PMID 30135298, 2018).
Non-bullous Congenital Ichthyosiform Erythroderma (4 papers, 2015 to 2025). "According to database of OMIM, the ALOXE3 gene mutations can cause autosomal recessive Nonbullous Congenital Ichthyosiform Erythroderma, so the mutation was causative for the proband." (PMID 26274329, 2015). "The involvement in the CLE assembly of eLOX-3 and 12R-LOX (enzymes, respectively, encoded by the ALOXE3 and ALOX12B genes) was considered because mutations within these genes are associated with the Non-bullous Congenital Ichthyosiform Erythroderma (NCIE)." (PMID 40981344, 2025).
colon adenocarcinoma (3 papers, 2021 to 2024). "The ALOX12 mRNA expression could be a diagnostic marker for colon adenocarcinoma and the expression of ALOXE3 combined with ALOX12 could have a prognostic value in colon adenocarcinoma." (PMID 35928873, 2022). "Finally, they reported that ALOXE3 and ALOX12 might serve as potential independent prognostic indicators of colon adenocarcinoma." (PMID 35928873, 2022).
congenital ichthyosis (3 papers, 2014 to 2023). "In the group of ARCI, NIPAL4 mutation is associated with a pronounced keratoderma, while ALOXE3 mutation is associated with an ichthyosis vulgaris-like pattern." (PMID 26762237, 2016).
psoriasis (3 papers, 2020 to 2025). An autoimmune condition characterized by red, well-delineated plaques with silvery scales that are usually on the extensor surfaces and scalp. "Some important ferroptosis driver genes, such as RPL8, NCOA4, and ALOXE3, are expressed at low levels in the keratinocyte population in psoriasis." (PMID 35962439, 2022).
atopic dermatitis (2 papers, 2019 to 2025). "We assumed that the increase of trihydroxy-linoleic acids in atopic dermatitis patients is due to the increased gene expression of enzymes involved in CLE formation, ALOX12B (12R-LOX), ALOXE3 (eLOX3), and ABHD9 (EPHX3)." (PMID 30608955, 2019).
breast carcinoma (2 papers, 2024). "The analysis of the GEPIA dataset revealed that ALOX15, ALOXE3, and HO‐1 exhibited higher expression levels, while ALOX12 showed lower expression levels in breast cancer tissues compared to normal tissues." (PMID 38516826, 2024). "In breast cancer, SBFI26, an inhibitor of FABP5, induces ferroptosis by elevating levels of ferrous ions and lipid peroxidation, increasing the expression of ALOXE3, ALOX5, and ALOX15, thus driving ferroptosis in tumor cells." (PMID 39633985, 2024). "Significant differences were observed in breast cancer tumour staging for ALOX5, ALOXE3, ALOX12, and ATF3 genes." (PMID 38516826, 2024). "The results revealed that breast cancer tissues exhibited lower expression levels of SAT1, ALOX5, ALOX12, ATF3, ATF4, GPX4 and NFE2L2 compared to normal tissues; conversely, higher expression levels of ALOX15, ALOXE3 and HO‐1 were observed in breast cancer tissues than in normal tissues." (PMID 38516826, 2024).
colon cancer (2 papers, 2022 to 2023). "Secondly, we studied the expression and pathophysiological significance of CYP19A1 in vitro and in vivo, and further studies are needed on other LMGs including FABP4, LRP2, SLCO1A2, PPARGC1A and ALOXE3 in colon cancer." (PMID 37055842, 2023). "Here we integrated CYP19A1, FABP4, LRP2, SLCO1A2, PPARGC1A and ALOXE3 with clinicopathological information of patients to construct a prognostic nomogram in colon cancer." (PMID 37055842, 2023). "Collectively, we screened the six LMGs including CYP19A1, FABP4, LRP2, SLCO1A2, PPARGC1A and ALOXE3, and constructed a signature to predict prognosis and immunotherapeutic response in colon cancer, which was extendedly and externally validated." (PMID 37055842, 2023). "In this study, we first used bioinformatics analysis to find that ALOXE3 is a ferroptosis-related gene and is differentially expressed in left-sided and right-sided colon cancer." (PMID 35265525, 2022). "Correlation between NOS2, ALOXE3 expression levels and clinicopathological characteristics of patients with colon cancer." (PMID 35265525, 2022). "They used multivariate survival analysis and comprehensive prognosis to show that ALOXE3 and ALOX12 were associated with colon cancer OS, the low expression of both is better for the prognosis of COAD, and ALOXE3 combined with ALOX12 may serve as a potential prognostic biomarker for COAD." (PMID 35265525, 2022). "Since the expression of ALOXE3 in colon cancer is closely related to tumor invasion and metastasis, we further analyzed the correlation between NOS2, ALOXE3 and clinical prognosis of patients." (PMID 35265525, 2022). "ALOXE3, PPARGC1A or FABP4 are prognostic biomarkers in colon cancer." (PMID 37055842, 2023). "On the other hand, we have not verified the cell experiments and mouse tumorigenesis experiments, and have not further explored the mechanism of NOS2, IFNG and ALOXE3 in the occurrence and development of colon cancer." (PMID 35265525, 2022).
Erythema (2 papers, 2015 to 2021). Redness of the skin, caused by hyperemia of the capillaries in the lower layers of the skin. "Patients with mutations in ALOX12B or ALOXE3 usually present with a mild phenotype including fine scaling and mild erythema." (PMID 33435499, 2021). "Taken together, our patient’s phenotype, including the presence of generalized erythema and the thick dark scaling over the joints in our patient, was reflective of his germline homozygous nonsense c.814C>T (p.(Arg272*)) variant in the ALOXE3 gene." (PMID 26370990, 2015). "The predominant clinical findings of most patients support the previous view of a mild phenotype including fine scaling and mild erythema in patients with ALOX12B and ALOXE3 mutations." (PMID 33435499, 2021).
lung carcinoma (2 papers, 2019 to 2023). "Neither of the first two genes shows tissue-matched oncogenic/TSG evidence and ALOXE3 only predicts poor prognosis in lung cancer." (PMID 36625266, 2023). "Every one standard deviation (SD) increase in DNA methylation at cg25365794 (ALOXE3 gene) resulted in a 19% decrease in incidence of lung cancer (HR (95%) 0.81 (0.66, 0.99))." (PMID 30678711, 2019).
alopecia (1 paper, 2015). Hair loss usually from the scalp. "Our sequencing results revealed that the genodermatosis was caused by a homozygous nonsense variant c.814C>T (p.(Arg272*)) in ALOXE3, which was complicated by a superimposed Trichophyton rubrum infection and associated alopecia." (PMID 26370990, 2015).
colorectal tumor (1 paper, 2022). "They showed that the expression level of ALOXE3, ALOX5, ALOX12, and ALOX12B was upregulated in colorectal tumor samples." (PMID 35928873, 2022).
congenital ichthyosiform erythroderma (1 paper, 2015). "Summary of reported variants in ALOXE3 (including the variant identified in our non-bullous congenital ichthyosiform erythroderma (NBCIE) patient of this study in bold)." (PMID 26370990, 2015).
coronary heart disease (1 paper, 2024). "We identified eight hub genes (CIRBP, USP7, ELAVL1, ATG13, ALOXE3, PRKAA2, USP11, SLC38A1) that exhibited significant differences between coronary heart disease (CAD) patients and healthy controls." (PMID 39610972, 2024).
dyslipidemia (1 paper, 2018). "Together, hepatocyte Aloxe3 expression was sufficient to reduce diet-induced weight gain, body fat accumulation, dyslipidemia, and insulin resistance." (PMID 30135298, 2018). "Moreover, hepatic Aloxe3 expression mitigated diet-induced dyslipidemia, and db/db mice expressing Aloxe3 exhibited attenuated weight gain, enhanced basal caloric expenditure, and PPARγ-dependent insulin sensitivity." (PMID 30135298, 2018). "Here, we show that Aloxe3 is activated by the adaptive hepatic fasting response and is itself sufficient to enhance insulin sensitivity, increase basal caloric expenditure, and reduce diet-induced weight gain and fat accumulation, hepatic steatosis, and dyslipidemia." (PMID 30135298, 2018).
esophageal cancer (1 paper, 2024). A primary or metastatic malignant neoplasm involving the esophagus. "However, the expressions of SLC27A5 and ALOXE3 were not significantly upregulated in esophageal cancer tissues compared to control tissues." (PMID 39633985, 2024).
glioma (1 paper, 2024). A benign or malignant brain and spinal cord tumor that arises from glial cells (astrocytes, oligodendrocytes, ependymal cells). "At the same time, some studies have proved that miR-18a promotes the occurrence and development of glioma by regulating the expression of CBX7, HMBOX1, and ALOXE3." (PMID 38879468, 2024).